S100B (S100 calcium binding protein B)
Diseases named in the same sentence as S100B in open-access papers (continued):
Sharing a sentence is not in itself a finding about the gene and the disease.
melanoma (continued). "This inhibition of RSK1 phosphorylation byS100B, coupled with its inhibition of the RSK1 C-terminal kinase domain,explains how S100B blocks the MAPK signal cascade via RSK1 in malignant melanoma." (PMID 30854023, 2018). "In line, at endpoint (day 18) the expression of S100B in lungs from melanoma-bearing animals was similar across genotypes despite pronounced differences in the primary tumour size." (PMID 29150606, 2017). "S100B has been reported as a useful biomarker in assessing tumor load, stage, and prognosis for patients with malignant melanoma." (PMID 28377727, 2017). "S100β is detected at low levels in human serum; however, elevated levels of serum S100β have been reported following injuries to the central nervous system and in different types of tumors including melanoma and breast cancer." (PMID 28399921, 2017). "In melanoma elevated serum levels of MIA (Melanoma Inhibitory Activity) and S-100B (beta) are associated with shorter survival and thus were useful as prognostic factors in stages III and IV disease and are elevated after recurrence of the disease." (PMID 27901477, 2017). "We show for the first time that SOX10 represents a promising new serum melanoma marker for detection of early stage disease, complementing the established S100B marker." (PMID 27110718, 2016). "We also tested MHA-3 on 227 melanoma patient samples and compared staining with the melanoma marker S100b." (PMID 27853253, 2016). "We detected elevated levels of both SOX10 and S100B, both in groups with thin melanoma in situ and in later stages of the disease." (PMID 27110718, 2016). "Many studies have been addressed in the attempt to enlarge the pharmacological knowledge on pentamidine and its novel therapeutic effects in disorders characterized by S100B upregulation, such as melanoma, glioblastoma, and colitis." (PMID 26295040, 2015). "On international level, serum S100B is also in the validation process, and, is a commonly used marker to pinpoint the prognosis of melanoma." (PMID 32309563, 2015). "A recent study on a large cohort of unresectable stage IV melanoma patients found S100B to be a better independent marker than LDH in terms of prediction of the long-term survival." (PMID 32309563, 2015). "Several biochemical markers are already clinically used to monitor progression and relapse of melanoma, such as S100B, MART1 and PMEL and S100A13." (PMID 25874936, 2015). "For melanoma, these methods include caliper measurements, measurements of a known biomarker, such as S100B or MIA, or immunohistochemical examination of treated tumors with H&E straining or antibodies directed against Ki67 and/or apoptosis markers." (PMID 25228592, 2014). "CMCs were identified by immunocytochemistry using Melan-A or S100B as melanoma markers and enumerated using automated microscopy image analyses." (PMID 24811334, 2014). "Typically, melanoma cells produced uniform or punctate cytoplasmic staining pattern for Melan-A and both cytoplasmic and nuclear distribution for S100B." (PMID 24811334, 2014). "We also followed mice undergoing treatment using blood sampling and measurements of human S100B levels, a clinical biomarker of melanoma growth and progression." (PMID 25228592, 2014). "In our analysis of 499 advanced melanoma patients with unresectable disease we found an independent prognostic impact of the S100B serum concentration in addition to the serum LDH." (PMID 24312329, 2013). "In the present review we discuss the field of proteomics in relation to studies elucidating biomarkers of UM, where proteins such as S-100β, osteopontin (OPN), and melanoma inhibitory activity (MIA) have been shown to be associated with metastasis." (PMID 24078811, 2013). "Serum S100B is a prognostic marker predicting survival at the time of initiation of first-line treatment in unresectable melanoma patients." (PMID 24312329, 2013).
melanoma (continued). "A large retrospective multicenter study of 692 malignant melanoma patients found that elevated serum S100B correlated with inferior overall survival, but only in the univariate analysis." (PMID 24179506, 2013). "In conclusion, the S100B serum level predicts overall survival in unresectable melanoma patients receiving systemic treatment." (PMID 24312329, 2013). "Other sources of the extreme S-100B levels, including encephalitis, new cerebral infarctions, and extra-cerebral sources such as malignant melanoma, were pursued." (PMID 23227020, 2012). "S100B protein is expressed by glial cells and melanocytes and has been shown to be produced by brain tumors and melanoma." (PMID 22287956, 2012). "One person with malignant melanoma showed a serum level of 126 μg/l, which was thought to be due to cell damage and necrosis of tumor sites, even S-100B levels as high as 221 μg/l have been reported in end stage melanoma patients." (PMID 23227020, 2012). "This case report studied the course of a 46-year-old gentleman with a chronic subdural hemorrhage, serum S-100B levels of 22 μg/l, and a history of malignant melanoma." (PMID 23227020, 2012). "LDH as well as S100B levels have been correlated with poor prognosis in AJCC stage III/IV melanoma patients." (PMID 22287956, 2012). "Here, we analyzed the correlation between sCEACAM1 and another known melanoma serum biomarker, S100B." (PMID 22291846, 2012). "S-100B is the most widely used biomarker in malignant melanoma patients where it is used to evaluate the efficacy of therapy." (PMID 23227020, 2012). "This case report of a gentleman with a chronic SDH, previous malignant melanoma, and sky-high S-100B levels serves as a reminder of potential extra-cerebral sources of error when utilizing S-100B as a biomarker." (PMID 23227020, 2012). "Among all these biomarkers, S100B emerges as a protein with an independent prognostic value in advanced melanoma, more specific and sensitive than LDH, as illustrated by some studies, but not yet ideal." (PMID 22287956, 2012). "We analyzed the predictive values, sensitivity and specificity of FDG PET/CT compared with the tumor markers S100B and MIA in the follow-up of high risk melanoma patients." (PMID 21935432, 2011). "Patients with elevated S100B- or MIA values or PET/CT positive findings showed a significantly (p<0.001 each, univariate Cox regression models) higher risk of melanoma associated death which was increased 4.2-, 6.5- or 17.2-fold, respectively." (PMID 21935432, 2011). "S100B, an immunohistochemical marker of pigmented skin lesions, has prognostic utility in melanoma—with rising concentrations of serum S100B (above >0.6 μg/L) indicating progression of the disease and a decline indicating response to treatment." (PMID 22220281, 2011). "It is widely accepted that S100B and MIA are of prognostic value in stratification of survival probability in high risk melanoma patients." (PMID 21935432, 2011). "TA90IC was compared to MIA and S100B in a prospective 75 patients study involving stage III melanoma patients undergoing adjuvant vaccine immunotherapy following completion of lymph node dissection." (PMID 22220281, 2011). "Increased amounts of S100B are also detected in tumours, e.g. in malignant melanoma and the S100B concentration correlates with the severity of the disease." (PMID 21445240, 2011). "S100B is also a well-established prognostic marker for melanoma and high serum concentration of S100B correlate with poor prognosis." (PMID 20672051, 2010). "In high risk melanoma patients, recent studies have investigated the use of PET/CT to detect recurrences in patients with elevated S-100B levels." (PMID 24281112, 2010).
melanoma (continued). "Based on cell integrity assay (lactate dehydrogenase release), the mechanism of S100B release from adipocytes should be appropriately referred to as S100B secretion, as occurs in astrocytes and differs, for example, from S100B release from melanoma cells." (PMID 20672003, 2010). "In melanoma, the most widely studied member of this family is S100B." (PMID 40869349, 2025). "Thus, S100B is a useful biomarker, which can be utilized as a prognostic tool and contribute to relapse detection in patients with melanoma." (PMID 40217072, 2025). "Therefore, developing efficient and sensitive methods for S100B detection is crucial for the early diagnosis of melanoma." (PMID 41459192, 2025). "Notably, S100B is among the serum protein biomarkers with the most robust clinical evidence supporting its role in melanoma surveillance, particularly for monitoring recurrence during follow-up." (PMID 40981345, 2025). "Furthermore, the expression level of S100B in lung tissue, whose high expression is highly correlated with melanoma metastasis and prognosis, was visibly lower in the CPIP@EV–CM + US group than the control group." (PMID 40854883, 2025). "A study found that MIA and S100B proteins could be isolated from melanoma-derived exosomes at concentrations that significantly correlated with serum concentrations." (PMID 39156972, 2024). "Serum levels of S100B are standard in monitoring advanced malignant melanoma patients." (PMID 39201780, 2024). "In the case of melanoma S100B and Melanoma Inhibitory Activity (MIA), antigens are present in exosomes and may be used for diagnosis and prognosis of the disease." (PMID 39519055, 2024). "We observed the benefit of the combination of protein tumor marker S100B and ctDNA BRAF oncogene in preoperative as well as postoperative peripheral blood samples for identification of patients with resectable melanoma (stage I–III) in high risk of recurrence and unfavorable prognosis." (PMID 39387479, 2024). "In our previous study, we found that pT4b primary tumor category, M1c stage or M1d stage at the start of therapy, elevated baseline serum S100B level, and elevated LDH level were associated with poor survival in patients with stage IV melanoma treated with anti-PD-1." (PMID 39272837, 2024). "This semi-quantitative correspondence in CRISPRdx signal could be attributed to the amount of detected ctDNA copies reflecting the amount of active melanoma cells, and thereby the S-100B levels." (PMID 39644903, 2024). "In this study, we hypothesize that multi‐omics testing, using both ctDNA as well as protein tumor biomarker S100B, may be beneficial as a prognostic biomarker of melanoma recurrence after surgery in early‐stage patients (stages 0—III, 48% in stages 0—IIA)." (PMID 39387479, 2024). "For instance, S100P and S100B have been associated with promoting metastasis, while S100A2 is underexpressed in certain cases, suggesting a more complex, context-dependent function in melanoma." (PMID 39769332, 2024). "The mean level of serum S100B in the whole melanoma group was 132.04 ± 224.43 ng/L (min." (PMID 37373887, 2023). "Furthermore, a significant correlation has been observed between the Breslow score and the serum S100B levels in patients with stage III melanoma." (PMID 38202181, 2023). "S-100β, melanoma-inhibitory activity (MIA), and osteopontin (OPN) serum concentrations, as well as concentrations of some growth factors and cytokines, might serve as important prognostic tools in UM." (PMID 37628989, 2023). "Thus, these prognostic factors, i.e., clinicopathological features of the primary melanoma, anatomic site of distant metastases, and baseline serum S100B and LDH levels are good candidates for a multivariable prognostic model, but validation is needed." (PMID 37664072, 2023).
melanoma (continued). "Overall, our data suggest that S100B suppression cooperatively works with the chemotherapeutic agents that trigger cell death by evoking apoptotic responses, thus potentially sensitizing melanoma cells to these inhibitors." (PMID 36899866, 2023). "Interestingly, serum levels of various microRNAs can discriminate between melanoma stages with increased accuracy compared to S100B or LDH." (PMID 37958863, 2023). "The chromatin state alterations of S100B in melanoma cells could be logically ascribed to overexpression of the gene because it does not seem to be expressed in primary keratinocytes at levels comparable to those in melanoma cells." (PMID 36899866, 2023). "For instance, S100B could serve as a strong baseline marker for survival in melanoma patients receiving anti-PD-1 immunotherapy." (PMID 37175874, 2023). "Moreover, 90.9% of the patients after tumor excision had a serum S100B level below the upper limit; these data support the sensitivity and specificity of the S100B protein in melanomas." (PMID 37373887, 2023). "It was hypothesized that Ir complexes might be able to interact and simultaneously monitor the S100B protein, which is expressed in the majority of melanoma tumors." (PMID 37345171, 2023). "Considering the regulatory role of activating transcription factors in S100B upregulation in melanoma, we stably suppressed S100b (murine ortholog) by using a catalytically inactive Cas9 (dCas9) fused to a transcriptional repressor, Krüppel-associated box (KRAB)." (PMID 36899866, 2023). "The expression of the S100B protein typically correlates with the grade of the melanoma." (PMID 37345171, 2023). "Lastly, in high-risk resected melanoma patients, serum LDH and S100B levels could predict prognosis." (PMID 37627153, 2023). "Overexpression of S100B and its clinicopathological relevance in melanoma has been well studied." (PMID 36899866, 2023). "LDH and S100B have been found to be reliable serum biomarkers in late-stage melanoma." (PMID 36140455, 2022). "However, the main clinical importance of S100B in the diagnosis of melanoma is the determination of its concentration in the blood serum." (PMID 36235175, 2022). "Additionally, S100B can serve as a marker for metastasis in lung cancer, ovarian cancer, melanoma, and breast cancer." (PMID 35368338, 2022). "With such data in mind, a model is discussed here in which elevated S100B may allow for melanoma cancer cells to escape immune detection by avoiding an early-stage IL6 dependent immune response in the tumor microenvironment." (PMID 34411141, 2021). "However, the different roles of S100B in supporting growth and survival of malignant melanoma are not fully understood." (PMID 34411141, 2021). "For these reasons, consequences of elevated S100B in malignant melanoma were studied further here." (PMID 34411141, 2021). "Harpio and Einarsson identified that high level of S100B is answerable for development of melanoma, but this gene might be identified with pituitary prolactinoma." (PMID 33709028, 2021). "S100B(ββ) is a clinically validated marker for malignant melanoma (elevated only in tumours) and traumatic brain injury (TBI) and has been associated with cancer progression in multiple myeloma (MM), NSCLC/SCLC, pancreatic cancer, etc., making it a potential target." (PMID 33573254, 2021).
melanoma (continued). "Indeed, the elevated S100B levels in malignant melanoma cell lines correspond to low levels of IL6 and p-STAT3." (PMID 34411141, 2021). "Thus, nuclear p-CREB (Ser133), IL6 expression, and IL6/STAT3 signaling were all restored upon S100B knockdown in WM115 melanoma cells." (PMID 34411141, 2021). "Based on our previously reported CRAF‐selective inhibitor for renal cancer therapy, we have herein discovered an analogue (complex 1) from the reported CRAF library suppresses melanoma cell proliferation and melanoma tumour growth in murine models of melanoma via blocking the S100B and RAF pathways." (PMID 33377602, 2021). "S100B is the most useful and standard biomarker for the follow-up of melanoma patients." (PMID 33256110, 2020). "S100B could also serve as a strong baseline marker of OS in patients with melanoma receiving anti-CTLA4 and/or anti-PD-1 antibodies." (PMID 32295074, 2020). "Moreover, progression of melanoma metastases secreting IL-6 should result in a parallel increase of both S100B and IL-6, thus imitating an immunologic response." (PMID 32188047, 2020). "Several serum proteins might have diagnostic and prognostic value for melanoma, including lactate dehydrogenase (LDH), S100B and melanoma-inhibiting activity (MIA)." (PMID 32295074, 2020). "However, in a study that compared different serum proteins in 373 patients with melanoma, serum S100B showed the highest sensitivity for newly diagnosed metastases (0.86), followed by MIA (0.80), LDH (0.48) and albumin (0.15)." (PMID 32295074, 2020). "MIA levels showed a good correlation with LDH levels in stage IV melanoma (as was the case for S100B), suggesting that serum MIA levels might be influenced by tumor burden." (PMID 31936623, 2020). "Investigating the molecular mechanisms of S100B in melanoma cells, it could be revealed that S100B interacts with ribosomal S6 kinase (RSK)." (PMID 32722137, 2020). "S100B has been described as the “lineage marker” of malignant melanoma." (PMID 33256110, 2020). "S100B serves as a prognostic factor and predictor of overall survival (OS) in melanoma patients." (PMID 33256110, 2020). "However, adding S‐100B measurement to standard clinical assessment can effectively guide FDG PET/CT scanning for detecting recurrent melanoma." (PMID 31468535, 2019). "This current study assessed the value of S‐100B measurement to guide fluorodeoxyglucose (FDG) positron emission tomography/computed tomography (PET/CT) scanning for detecting recurrent disease in stage III melanoma patients." (PMID 31468535, 2019). "Moreover, immunohistochemical (IHC) assessments of prognostic factor Ki67, HMB‐45, and S‐100B expression further confirmed that melanoma cells invaded in sentinel lymph node and distant spleen." (PMID 30886812, 2019). "Clearly, S‐100B measurement cannot exclude disease during follow‐up of stage III melanoma." (PMID 31468535, 2019). "However, adding S‐100B measurement to standard clinical assessment can guide FDG PET/CT scanning for detecting recurrent melanoma." (PMID 31468535, 2019). "Therefore, we conclude that the addition of S‐100B measurement in the follow‐up of stage III melanoma prompted detection of stage IV disease in 10% of all asymptomatic stage III patients, and resulted in 23% additional upstaging." (PMID 31468535, 2019). "S100B could serve as a strong baseline marker for OS in melanoma patients receiving anti-PD-1 therapy." (PMID 29950611, 2018). "S100B plays a prognostic role in the majority of brain metastases of melanoma." (PMID 29607329, 2018).